SMO (smoothened, frizzled class receptor)
Diseases named in the same sentence as SMO in open-access papers (continued):
Sharing a sentence is not in itself a finding about the gene and the disease.
meningioma (continued). "Molecular analysis revealed that there were 152 NF2 meningiomas (54.1%) and non-NF2 meningiomas: 45.9% (129 cases) including “AKT1”: 11.4% (32 cases), “KLF4”:5.7% (16 cases), “POLR2A”:16 cases (5.7%), “SMO”: 0.7% (2 cases), and others:22.1% (62 cases)." (PMID 35570314, 2022). "The 2021 WHO classification criteria incorporates 10 genes that are frequently altered in meningiomas, including NF2, AKT1, TRAF7, SMO, PIK3CA." (PMID 35712492, 2022). "Additional common pathological relevant genes of meningiomas, including AKT1 (n = 3; 8%), CDKN2A (n = 2; 5%), SMO (n = 0; 0%), SUFU (n = 0; 0%), POLR2A (n = 6; 16%), TRAF7 (n = 1; 3%), and SMARCB1 (n = 2; 5%), were observed as well." (PMID 34778063, 2021). "Of note, other common pathological relevant genes of meningiomas, including AKT1 (n = 3; 8%), CDKN2A (n = 2; 5%), SMO (n = 0; 0%), SUFU (n = 0; 0%), POLR2A (n = 6; 16%), TRAF7 (n = 1; 3%), and SMARCB1 (n = 2; 5%), were detected as well." (PMID 34778063, 2021). "Overall, these results confirm the high frequency of genetic variants of the NF2 gene and to a less extent also of the PTEN, SMO, and POLR2A genes, in WHO grade 1 meningiomas." (PMID 34868937, 2021). "In addition, recent genomic analyses of meningioma using next-generation sequencing have identified mutations in the TNF receptor-associated factor 7 (TRAF7), the Kruppel-like factor 4 (KLF4), the v-Akt murine thymoma viral oncogene homolog 1 (AKT1), and the smoothened (SMO) gene." (PMID 32742192, 2020). "Other common driver mutations in our cohort such as CDKN2A, ARID1A, BRCA1, NF1, AKT1, SMO, PIK3CA have similarly been noted in various prior sequencing studies of meningiomas." (PMID 31191822, 2019). "NF2 mutant meningiomas are in all grades including WHO grade II and III whereas SMO, TRAF7, TRAF7/AKT1 and KLF4 meningiomas tend to be WHO grade I." (PMID 30082628, 2018). "Inhibitors of recently identified meningioma oncogenes, including AKT1, SMO, and PIK3CA, are now in clinical trial for recurrent and progressive meningiomas." (PMID 28923059, 2017). "Inhibitors of SMO, AKT1, and PIK3CA hold promise as molecularly targeted pharmacotherapy in meningioma." (PMID 27458586, 2016). "CDKN2A deleted meningiomas did not harbour SMARCB1, AKT1, PIK3CA, SMO, POLR2A, or RB1 somatic mutations." (PMID 37093270, 2023). "Transcriptional and multiplexed immunofluorescence results between Hh ligand and SMO mutant meningiomas were indistinguishable based on interrogation of well-established Hh signaling markers." (PMID 37805627, 2023). "Mutations common in non-chordoid low grade meningiomas, such as AKT1 and SMO, were also sparse or absent." (PMID 35440040, 2022). "Five IVMs were included in another study performing whole-genome sequencing of 775 meningiomas; two cases had NF2 mutation, one featured SMO mutation and no other mutations were found." (PMID 35049691, 2022). "BAP1 mutant meningiomas localize to cerebral convexities, while SMO mutant meningiomas are located in the anterior skull base, but not midline." (PMID 36033542, 2022). "Immunofluorescence of a primary meningioma cell line derived from the resection specimen (SF13398) showed SMO accumulation in primary cilia did not increase in response to recombinant Sonic Hedgehog stimulation." (PMID 36382111, 2022). "Genomic sequencing was also performed and mutations in NF2, TRAF7, SMO, KLF4, and AKT1 did not predict RB1 S780 staining or progression in grade 1.5 meningiomas." (PMID 33346248, 2020). "In our dataset of tumours, all the SMO L412F mutant tumours were observed exclusively as convexity supratentorial tumours and meningothelial subtypes, while the PIK3CA H1047R mutant tumours were sphenoid wing meningiomas." (PMID 32070062, 2020). "NF2 mutations were found in 44% of the cases, while common genetic alterations in meningiomas of other locations (TRAF7, AKT1, SMO, KLF4, PIK3CA, and TERT) were lacking in non-NF2-associated cases." (PMID 31470906, 2019).
meningioma (continued). "POLR2A-mutant meningiomas do not exhibit mutations in other meningeal driver genes, such as NFE2, TRAF7, KLF4, AKT1, or SMO." (PMID 30279357, 2018). "Lastly, ~5.5% of benign meningiomas, or more than 10% of meningiomas without NF2 alteration, express mutations in SMO." (PMID 27458586, 2016). "Additionally, alterations in other genes such as SMO, AKT1, TRAF7, and KLF4 have been identified, particularly in non-NF2 mutant meningiomas, indicating a heterogeneous molecular landscape that may influence both prognosis and treatment response." (PMID 41007735, 2025). "Like meningiomas or certain ovarian cancer cells, there may be gliomas whose cilia can translocate SMO but do not trigger downstream events." (PMID 37830570, 2023). "Notably, the PIK3CA-mutant meningiomas lacking mutations in NF2, AKT1, and SMO, tend to express TRAF7 mutations." (PMID 35565385, 2022). "Moreover, a national Alliance-sponsored cooperative group phase II clinical trial evaluated the efficacy of SMO, AKT1, and FAK inhibitors for recurrent or progressive meningiomas with targetable alterations in SMO, AKT1, and NF2, respectively (NCT02523014/A071401)." (PMID 35712491, 2022). "In addition, 1–5% of meningiomas without alterations in NF2 and AKT1, harbor mutations in the SMO gene, which encodes smoothened homolog, a member of the Hedgehog signaling pathway." (PMID 35565385, 2022). "SMO and AKT1 in particular are primarily found in meningothelial or transitional WHO grade I meningiomas, are rare in WHO grade II lesions, and absent in WHO grade III meningiomas." (PMID 34638590, 2021).
breast carcinoma (45 papers, 2013 to 2025). "A preclinical trial has shown that targeting GLI1 exhibits an anti-tumor effect and efficiently overcomes the tumor resistance caused by SMO inhibitors in breast cancers." (PMID 35805056, 2022). "Somatic mutations in the SMO gene have also been identified in breast cancer." (PMID 27557076, 2016). "In previous work, it has been demonstrated that CAXII expression is related to the Hh pathway, as inhibition of SMO determined its downregulation in breast cancer." (PMID 38399442, 2024). "EVC2 positively modulated Hedgehog (Hh) signaling pathway by forming complex with SMO protein and transduced Hh signaling in recipient breast cancer cells." (PMID 35148692, 2022). "Their expression levels were all higher in breast cancer tissue than in normal breast tissue, with more than a two-fold difference for SMO, GLI1, and GLI2." (PMID 36142286, 2022). "A direct induction of GLI2 protein expression by TGF-β1 was observed in dermal fibroblasts, keratinocytes and breast carcinoma cells in an SMO-independent manner." (PMID 33440657, 2021). "JAK2 inhibitors cooperate with SMO inhibitors to inhibit the growth and metastasis of breast cancer cells." (PMID 33664765, 2020). "Consistent with our results, Bei and colleagues found that GANT61 inhibited Hh pathway activity and breast cancer cell survival more effectively than GDC-0449 (a SMO inhibitor)." (PMID 32391382, 2020). "Cyclopamine, a naturally occurring chemical with a high affinity for SMO, can be used to block Hh pathway signaling and can reduce breast cancer cell viability." (PMID 32391382, 2020). "The researchers found that in breast cancer, downstream SMO targeting is better than upstream SMO when attempting to interrupt SHH signaling." (PMID 31979397, 2020). "Instead, we found that GANT61, a GLI antagonist which interferes with GLI translocation to the nucleus, is more efficacious in PDX models of breast cancer than SMO inhibitors." (PMID 32391382, 2020). "Recently, SMO methylation was used as a biomarker for the occurrence and development of breast cancer." (PMID 32784501, 2020). "The HH/SMO signaling pathway plays an important role in breast cancer development, progression, invasion and metastasis." (PMID 32962123, 2020). "Although SMO inhibitors show promising results in these patients, they have been less efficacious as single agents in other solid tumours such as breast cancer, despite evidence for activated Hh signalling." (PMID 28604738, 2017). "PTCH1 protein levels are reduced in 50% of DCIS and invasive breast cancer (IBC), whereas 70% of DCIS and 30% of IBC display aberrant SMO, suggesting that hedgehog activation occurs frequently and early in human breast cancer." (PMID 28275010, 2017). "Next, the in vitro effects of two Hh signaling pathway inhibitors on breast cancer cell lines were evaluated using the Smoothened (SMO) antagonist GDC-0449 and the direct GLI1 inhibitor GANT-61." (PMID 26843616, 2016). "The non-classical mode of activation is independent of Hh ligand presence, which occurs irrespective of PTCH receptors loss of function or gain of function of SMO; this mode is found in BCC, and can occur in breast cancer." (PMID 26988232, 2016). "High levels of SMO and Gli-1 expression have been found to correlate with continuous activation of breast cancer stem cells in TNBC patients samples." (PMID 26389956, 2015). "In this study, we observed that activated LKB1 decreased the expression of factors related to Hh reporter activity in MDA-MB-231 breast cancer cells, including of SMO, SHH and GLI1." (PMID 23861764, 2013). "Consequently, SMO has become a strategic target in the treatment of several cancer types, including breast cancer." (PMID 37174034, 2023). "For instance, FOXC1, which is active in BCC-I, can activate SMO-independent HH signaling in basal-like breast cancer, suggesting that it may regulate BCC drug resistance." (PMID 35687691, 2022).
breast carcinoma (continued). "In addition to PTCH1, high SHH, SMO, GLI1, and GLI2 expression levels were all associated with a poor prognosis in breast cancer patients." (PMID 36142286, 2022). "The ability of the Wnt pathway to promote GLI1, and potentially tGLI1, activation in combination with the limited efficacy of SMO inhibitors in breast cancer clinical trials provides the rationale for directly targeting tGLI1 as a potential therapeutic modality." (PMID 36077791, 2022). "Notably, high levels of Shh and GLI1 have been associated with the enhanced acquisition of CSC traits and chemoresistance in breast cancer, which can be attenuated with SMO inhibitors." (PMID 34572373, 2021). "Interestingly, inhibition of both SMO and osteopontin resulted in greater suppression of the expression of ABC transporters, which suggests a cooperative role of both SMO-dependent and SMO-independent axis in promoting breast cancer chemoresistance." (PMID 34572373, 2021). "Therefore, downstream SMO targeting seems to be superior to upstream SMO targeting in interrupting the HH signaling in breast cancer." (PMID 32962123, 2020). "In particular, TGF-β may induce GLI1 expression in a GLI2-dependent manner independently from SMO in breast cancer." (PMID 29456503, 2017). "Recently, two groups have shown that hedgehog signaling may be active in a subset of human breast cancer cell lines, and that SMO antagonists can inhibit breast cancer growth." (PMID 27557076, 2016). "Pending formal presentation of all study results, preliminary findings suggest limited therapeutic efficacy, and with early closure of two of the breast cancer trials, it is unlikely that we will gain further insight into the clinical value of SMO inhibitors in TNBC." (PMID 27539549, 2016). "Thus, GLI1 activation by SMO-dependent or -independent mechanisms in breast cancer cells could promote EMT-like changes and stemness acquisition, resulting in enhanced metastatic potential and chemoresistance." (PMID 34572373, 2021). "Besides hematological-related malignancies, solid tumors such as pancreatic, gastric, breast cancer, and lung cancer may benefit from treatment with specific SMO inhibitors." (PMID 34572373, 2021). "Additionally, mutations that result in overproduction of Hh ligands in breast cancer and BCC, loss of PTCH receptor function in BCC and gastric cancer, as well as upregulation of SMO activity in pancreatic cancer stroma and BCC can lead to constitutively activated Hh signaling." (PMID 26988232, 2016). "In pancreatic and breast cancers, AKT-driven GLI1 activation promotes tumour stemness and chemoresistance, even in the presence of SMO inhibitors." (PMID 40426308, 2025). "We also observed that the accumulation of lactate significantly increased SHH, SMO, and GLI1 expression of the SHH signaling pathway in breast cancer cells." (PMID 36737428, 2023). "First, we analyzed the expression of SHH, PTCH1, SMO, GLI1, and GLI2 in normal breast and breast cancer tissues through the Oncomine database." (PMID 36142286, 2022). "We found that normal breast tissue and breast cancer tissue expressed significantly different levels of SHH, PTCH1, SMO, GLI1, and GLI2 (p < 0.05)." (PMID 36142286, 2022). "SMO and GLI1 were detected in CTCs from breast cancer patients by immunohistochemistry and RNA in situ hybridization and used as markers of the heterogeneity of the CTCs." (PMID 33440657, 2021). "Overexpression of Hedgehog molecules SMO and GLI1 exists in breast cancer and mammary hyperplasia, which can affect histological grade or tumor stage in TNBC." (PMID 32962123, 2020). "Plasmids containing SMO gene fragments were transiently transfected into three cancer cell lines (prostate cancer line PC3; breast cancer lines BT549 and MCF7), and the luciferase activities of these constructs were measured." (PMID 32784501, 2020). "Therefore, targeting SMO could be an effective way to treat breast cancer." (PMID 32962123, 2020).
breast carcinoma (continued). "SMO inhibitor cyclopamine decreased SMO, GLI and CD44 expression and reduced cell proliferation of breast cancer stem cells for chemoresistance." (PMID 32962123, 2020). "SHH/SMO inhibitors have been shown to inhibit the CSCs of some cancers, including pancreatic cancer (ALDH+ cells), colon cancer (CD133+ cells), breast cancer (CD44 +CD24− cells) and gastric cancer (CD44+ cells)." (PMID 32962123, 2020). "We noted a consistent increase in the expression of SHH, SMO and GLI1 that correlated with the level of tamoxifen resistance in breast cancer cell lines." (PMID 31394751, 2019). "In a metastasis model of breast cancer cells MDA-MB-231, SMO-independent induction of GLI2 is required for TGF-β to stimulate the expression of parathyroid hormone-related protein (PTHrP), an important osteolytic factor in bone metastasis." (PMID 31244888, 2019). "Few SMO inhibitor trials on solid tumors have allowed enrollment of breast cancer patients and only three studies (NCT01071564, NCT01757327, and NCT02027376) investigated the use of SMO inhibitors, alone or in combination, exclusively in breast cancer." (PMID 27539549, 2016). "Currently, combinations of FDA-approved JAK2 inhibitors, including ruxolitinib (Rux) and pacritinib (Pac), and SMO inhibitors including vismodegib (Vis) and sonidegib (Son) exerted synergistic cell kill in a HER2-positive breast cancer cell lines with acquired trastuzumab resistance." (PMID 37174034, 2023). "In the transgenic MMTV-ErbB2 (HER2-positive) mouse model, ΔNp63 supports breast cancer stemness by inducing the elevation of the SHH signaling cascade, inducing the expression of Smoothened (SMO), Protein Patched Homolog 1 (PTCH1), and GLI Family Zinc Finger 2(GLI2)." (PMID 35805056, 2022). "Therefore, we used the Kaplan–Meier plotter website to analyze the effects of SHH, PTCH1, SMO, GLI1, and GLI2 on the prognosis of breast cancer patients." (PMID 36142286, 2022). "Cyclopamine, a potent hedgehog signaling antagonist, inhibits breast cancer proliferation independent of SMO." (PMID 33352739, 2020). "Cell lines from breast cancer tissue showed the highest methylation frequency, 56% (5/9), whereas eight prostate cancer cell lines had no detectable methylation in the SMO gene." (PMID 32784501, 2020). "Cyclopamine, a potent Hedgehog signaling antagonist, inhibits breast cancer growth independent of SMO." (PMID 32033067, 2020). "Another SMO inhibitor, sonidegib, which is FDA-approved for the treatment of advanced and metastatic basal cell carcinoma, was evaluated in phase I and II clinical trials for patients with breast cancer." (PMID 32391382, 2020). "Moreover, full methylation was confirmed in all three CpG islands in the MCF7 breast cancer cell line, and stomach cancer cell line AGS, and SMO expression in MCF7 cells were restored after 1 μM 5-Aza treatment." (PMID 32784501, 2020). "Interestingly, we found that Gli1 was significantly up‐regulated in breast cancer tissues, whereas PTCH1, SMO, Gli1 and HHIP at mRNA and protein levels were all down‐regulated after controlling for EGOT overexpression." (PMID 32150666, 2020). "Moreover, GLI1 (GANT61) but not SMO (GDC-0449 and LDE225) inhibition significantly reduced FOXC1-induced GLI-BS-luciferase activity in both SMO-positive and SMO-negative breast cancer cell lines, suggesting an SMO-independent activation of GLI." (PMID 34572373, 2021). "In addition, the absence of SMO expression was confirmed in seven cell lines, including five breast cancer cell lines and the stomach cancer AGS cell line, whereas the lack of SMO was accompanied by undetectable GLI3 in colon cancer HT29 cells." (PMID 32784501, 2020). "Our previous studies showed that GLI signaling is activated downstream of EMT transcription factors in both SMO-dependent and SMO-independent manners, providing a potential explanation for why SMO inhibitors are not efficacious in breast cancers with evidence of activated Hh signaling." (PMID 32391382, 2020).
breast carcinoma (continued). "Such evidence suggests that targeting downstream molecules of SMO when treating breast cancer may not be effective." (PMID 31979397, 2020). "Our previous results with a breast cancer cell line showed no alteration in SHh expression as promoted by different oxysterols; however, 7-KC and cholestan-3α-5β-6α-triol were able to increase the expression of SMO in the nucleus." (PMID 31117185, 2019). "Specifically, the role of canonical, SMO-/SHH-dependent HH signaling and non-canonical, SMO-/SHH-independent HH signaling was addressed, as this pathway has been linked to tumorigenesis including breast cancer." (PMID 26927093, 2016). "The database analysis of the Hedgehog pathway markers (SHH, PTCH1, SMO, GLI1, and GLI2) revealed that the Hedgehog pathway is activated in breast cancer tissues, and its high expression is not conducive to a patient’s survival." (PMID 36142286, 2022). "This is consistent with previous reports that identified overexpression of SMO and GLI2 in progesterone receptor (PR) negative breast cancers and gastric cancers." (PMID 32784501, 2020). "Importantly, we demonstrate that in selected patient-derived breast cancer xenograft (PDX) models, GANT61 (a GLI1/2 inhibitor) inhibits tumour growth, whereas IPI926 (a SMO inhibitor) does not." (PMID 28604738, 2017).